TNF (tumor necrosis factor)
Diseases named in the same sentence as TNF in open-access papers (continued):
Sharing a sentence is not in itself a finding about the gene and the disease.
bacterial infection (continued). "The serum levels of PCT of the patients with bacterial infections correlated positively with IL-1Ra (r = 0.725; P = 0.001), TNF-α (r = 0.659; P = 0.004), and MCP-1 (r = 0.556; P = 0.011)." (PMID 23690657, 2013). "The addition of MSX-122 to the culture media during the bacterial infection significantly attenuated the amount of TNF-α induced by these strains, suggesting that CXCR4 plays crucial roles in the host response to the CD-isolated invasive E.coli." (PMID 22485156, 2012). "AAM have also been shown to produce TNFα which can be enhanced by bacterial infection or LPS treatment." (PMID 22292924, 2012). "TNFα is a cytokine that mediates inflammatory response during wounding, chronic inflammation, and bacterial infection." (PMID 22947142, 2012). "Several activities of the transmembrane form of TNF (memTNF) in immune responses to intracellular bacterial infection have been shown to be different from those exerted by soluble TNF." (PMID 22666310, 2012). "Conversely, a number of cells (e.g., macrophages and mast cells) and mediators (e.g., TNF-α and IL-6) improve host survival following severe bacterial infections." (PMID 22110673, 2011). "We analyzed mRNA levels for these adhesion molecules in PCPECs under bacterial infection with S. suis strain 10 and its isogenic mutant strain 10 Δcps and after TNFα stimulation, using quantitative real time-PCR." (PMID 21592385, 2011). "There is some modest supporting evidence from a trial of simvastatin in suspected or proven bacterial infection; reductions in tumor necrosis factor-α and interleukin-6 were demonstrated in the statin treated arm." (PMID 21541017, 2011). "PCT is produced ubiquitously in response to endotoxin or mediators released in response to bacterial infections (that is, interleukin (IL)-1β, tumor necrosis factor (TNF)-α, and IL-6) and strongly correlates with extent and severity of bacterial infections." (PMID 21936959, 2011). "We previously showed that human odontoblasts increased transcription of pro-inflammatory cytokines, IL-1β and TNF-α in response to bacterial infection in vitro." (PMID 21261944, 2011). "Both interleukin (IL)-1β and tumor necrosis factor (TNF)α are cytokines produced by the intrauterine tissues in response to bacterial infections which stimulate prostaglandin synthesis and increase uterine contractility." (PMID 21192811, 2010). "It has been reported that under the circumstances of inflammation, or upon bacterial infection, the increased release of inflammatory cytokines such as IL-1β and TNF-α have potent effect on up-regulation of CFTR in epithelial cells." (PMID 21151921, 2010). "In particular, while oscillations of NF-κB activation have been observed in response to the cytokine tumor necrosis factor α (TNFα), little is known about the occurrence of oscillations in response to bacterial infections." (PMID 20233427, 2010). "Consistent with the data presented in this study, TLR-4 signaling and activated macrophages are capable of producing and responding to IL-1β and TNF-α to fight against bacterial infection." (PMID 20565713, 2010). "Among these responses, the production of inflammatory mediators such as tumor necrosis factor (TNF) and interleukin (IL)-6 as well as reactive oxygen species such as nitric oxide (NO) play important roles in protecting the host against bacterial infection." (PMID 19108715, 2008). "TNF-α is released by cells under various stimuliincluding bacterial infections or ultraviolet radiation." (PMID 18584045, 2008). "IL-1, TNF-α, IL-6 are the early pro-inflammatory cytokines produced by monocytes after various bacterial infections and share a wide array of biological activities." (PMID 16504020, 2006). "We next examined whether D. pinnata extract could suppress TNF-α expression induced by bacterial infection, a potent trigger of inflammatory signaling." (PMID 41596763, 2026).
bacterial infection (continued). "Notably, in vivo bacterial infection model, QRs increased the proportion of M2 macrophages, stimulated endothelial cell proliferation, reduced the secretion of TNF-α and IL-6 in the tissue microenvironment, and accelerated the rapid healing of wound tissue." (PMID 40612279, 2025). "Furthermore, TNFα and IL-1α play crucial roles in inducing chemokines and recruiting MΦs and T cells necessary for eliminating intracellular bacterial infections and maintaining the protective microenvironment of tuberculous granulomas." (PMID 41189022, 2025). "Notably, pathway-based differential co-expression test indicated a significant disruption of systemic autoimmune disease TNF-α signalling, bacterial infection pathways, and antigen processing cross presentation (FDR < 0.05) by allele." (PMID 41022800, 2025). "The activation of an innate immune system (involving monocytes and macrophages) by viral/bacterial infections or tissue damage results in the secretion of inflammatory mediators, such as nitric oxide (NO), tumor necrosis factor-α (TNF-α), and interleukin-6 (IL-6)." (PMID 40723879, 2025). "TNF-α is an important contributor to host defense against bacterial infections." (PMID 38780542, 2024). "Moreover, SP supplementation alone or mixed with Bacillus licheniformis enhanced the transcriptional levels of Lysozyme, Il-6, Il-1β, Tgf, and TNF-α, which in turn increased the goldfish resistance to bacterial infection and lowered its mortality rate." (PMID 39453066, 2024). "Thus far, this study has shown that TNF regulates NK cell function during bacterial infection in mice." (PMID 39543125, 2024). "Cytokines such as IL‐1β, IL‐2, IL‐5, IL‐6, IL‐8, IL‐12p70, IL‐17, and TNF‐α may be involved in the progression of COVID‐19 combined with bacterial infection." (PMID 39692539, 2024). "The impaired healing of diabetic wounds can also be attributed to the severe inflammation induced by bacterial infection, leading to the impairment of angiogenesis as well as excessive production of pro-inflammatory cytokines, such as interleukin(IL)-6, IL-1β and tumor necrosis factor-α (TNF-α)." (PMID 38519957, 2024). "Since TNF-α is a known proinflammatory cytokine that regulates macrophage function and these macrophages are protective factors against bacterial infection, it seems reasonable that TNF-α expression is induced by EHEC infection in vivo in mice and in vitro in dogs." (PMID 39162490, 2024). "Similarly, KEGG pathway analysis of these target genes revealed several enriched immune-related pathways, such as the TNF signaling pathway, bacterial infection, IL-17 signaling pathway, and hematopoietic cell line." (PMID 38457553, 2024). "In the patient reported here, the preserved TLR function might prevent systemic bacterial infections despite abrogated TNF response." (PMID 39264518, 2024). "Anti-TNF therapy can also increase the likelihood of viral or bacterial infections, which may promote different autoimmune reactions, such as molecular mimicry, bystander activation, or epitope spreading." (PMID 39421866, 2024). "In summary, we provide an extensive description of the monocyte-derived pro-inflammatory cytokine responses by preterm newborns and show that TLR-mediated production of TNF-α and IL-6 in the context of bacterial infections is comparable between preterm neonatal, term neonatal and adult WB." (PMID 38562936, 2024). "The cytokines TNF-α, IL-1α and IL-6 promote the synthesis of acute phase proteins such as C-reactive protein, by hepatocytes, the concentration of which is significantly increased during bacterial infection or tissue damage." (PMID 36937280, 2023). "Melittin may play an anti-RA role through TNF, IL-17, TLR, and AGE–RAGE signaling pathways, and pathogenic bacterial infection." (PMID 37565866, 2023).
bacterial infection (continued). "Elevated concentrations of IL-1β, IL-6, and TNF-α in children may be correlated with OM; in particular, IL-6, a marker of a bacterial infection, can induce C-reactive protein (CRP) production and appears to play a vital role in inflammation in OM." (PMID 36911197, 2023). "Although interferon-g (IFN- g) production can be maintained in ESRD patients by stimulating MAIT cells with IL-12 or IL-18, low levels of tumor necrosis factor (TNF) production in response to microbial activation suggest that the response to bacterial infection is dysfunctional." (PMID 37123717, 2023). "TNF-α is a type II homotrimeric membrane protein that plays a key regulatory role in inflammation and host defense against bacterial infection, and IL-1β is a multifunctional cytokine involved in many immune and pro-inflammatory responses." (PMID 37251563, 2023). "Additionally, TNF-α is a typical inflammatory cytokine involved in type 1 immune response against bacterial infections and plays a crucial role in OD pathogenesis by mediating the progressive loss and regenerative inhibition of olfactory sensory neurons." (PMID 37292198, 2023). "However, in response to pro-inflammatory cytokines, tumor necrosis factor-alpha (TNF-α) and interleukin-1, and bacterial infection, it rapidly increases from 10 to 100 fold base value." (PMID 37340381, 2023). "And as stated by Lippi and Plebani, the production and release into circulation of procalcitonin from extra-thyroid sources are greatly amplified during bacterial infections, actively supported by increased concentrations of interleukin (IL)-1β, tumor necrosis factor (TNF)-α, and IL-6." (PMID 36590954, 2022). "First, bacterial infection can augment the autoimmune response: Streptococcus combined with Veillonella isolated from the human small intestine microbiota inhibited IL-12p70 production and augmented IL-8, IL-6, IL-10 and TNF-α responses." (PMID 35847775, 2022). "Moreover, inflammatory factors such as TNF-α and IL-6 were dramatically decreased after Nano-MgB2 treatment, further demonstrating decreased bacterial infection and inflammation in Nano-MgB2-treated wounds." (PMID 36446788, 2022). "American large claims data including a population aged 65 years or older showed that TNF inhibitor use was not a significant risk factor for serious bacterial infection." (PMID 35689250, 2022). "In addition, Ogg1 knockout mice exhibited reduced serum IgG2a levels in response to bacterial infections, accompanied by reductions in the expression of chemokine Mip-1α the Th1 cytokines interleukin-12 (IL-12) and tumor necrosis factor-α (TNFα)." (PMID 36497058, 2022). "The bacterial infection and excessive amount of local proinflammatory mediators such as TNF-α and IL-6 that are produced in in response to the bacterial lipopolysaccharide, LPS, can ultimately trigger a severe systemic illness leading to animal prostration and death." (PMID 36230275, 2022). "M1 activation, as induced by viral and bacterial infections, is characterized by the production of ROS and proinflammatory mediators, such as IL-1β (interleukin one beta), TNF-α (tumor necrosis factor alpha) and IL-6 (interleukin 6), which provide a robust microbe-killing activity." (PMID 35431927, 2022). "Although most of the LPS is detoxified by immune cells at the site of inflammation, severe bacterial infection can increase the permeability of the blood-milk barrier, allowing LPS, proinflammatory cytokines (mainly TNF-α and IL-1β) and toxic metabolites to enter the bloodstream." (PMID 36230275, 2022). "Systemic PCT production is triggered by bacterial toxins (endotoxin) and by pro-inflammatory cytokines such as tumor necrosis factor (TNF)-α, interleukin-1-β (IL-1β), and interleukin-6 (IL-6) as an immunological danger signal able to alert the host of a possible bacterial infection." (PMID 34195086, 2021).
bacterial infection (continued). "On the other hand, triggered by viral or bacterial infections, the production of TNFα, IL-6, IL-1β, and INFγ may amplify the ER stress in many cell types including macrophages, pancreatic β cells and hepatocytes." (PMID 34834808, 2021). "STFX may be an effective drug for patients with bacterial infections because of its antimicrobial action and the simultaneous reduction of TNFα." (PMID 34921186, 2021). "TNF-α is produced by activated monocytes/macrophages and is synthesized in large quantities during the acute phase of bacterial infection, subsequently promoting the activation of downstream immune cells, such as T cells, thus intensifying the inflammatory response and harming the host." (PMID 34746321, 2021). "Similarly, recent studies have shown that B. subtilis can reduce intestinal inflammation by modifying the polarization of macrophages, inhibiting the expression of TNF-α, and thus protecting the body from bacterial infections." (PMID 34746321, 2021). "Since cytokines released by monocytes pivotally determine survival during bacterial infections, we analysed induction of IL-6, IL-1beta and TNF-alpha separately in TLR-stimulated classical CD14++CD16−, intermediate CD14++CD16+ and non-classical CD14+CD16++ monocytes." (PMID 33278000, 2021). "Contrastingly, a meta-analysis of randomized controlled trials of the safety of TNF blockers in over 8,800 RA patients did not identify an increased risk of serious bacterial infection in the standard recommended dose." (PMID 34790122, 2021). "Moreover, viable bacterial infection also induced more NO and TNF-α production in RAW264.7 cells than heat-killed bacterial infection." (PMID 34491082, 2021). "This stimulation activates the transcription factor NF-кB, a protein complex that is crucial for the production of pro-inflammatory cytokines such as IL-1, IL-6 and TNF-α, which are important for the response to bacterial infections and the induction of sickness behaviour." (PMID 32717860, 2020). "Interestingly, in vitro phage therapy using bacteriophage K1F against E. coli EV36 infection of hCMEC cultures resulted in a reduction in TNFα expression of approximately 50% compared to bacterial infection alone." (PMID 32483257, 2020). "Macrophages polarize to M1 response to kill the invading pathogens (such as Salmonella typhi, Salmonella typhimurium, and Mycobacterium tuberculosis, etc.)by the production of various proinflammatory cytokines including TNF-α, IL-6, and IL-1β in the early stage of bacterial infection." (PMID 33585271, 2020). "The production of IFNγ, TLR ligands, TNF-α, PGE2, IL-1β, and IL-6 from T cells or bacterial infection may follow the accumulation MDSCs associated with signal transducer and activator of transcription signaling pathways." (PMID 33212789, 2020). "TNFα plays a key role in the defense against bacterial infections." (PMID 32045425, 2020). "Mesothelial cells in vivo can produce TNFα in response to bacterial infection." (PMID 33374405, 2020). "Elevated serum IL-6 and TNF-α are capable of predicting the severity of bacterial infection." (PMID 31938070, 2020). "Here, we measured up to a 6-log increase of the TNF-α mRNA-expression after bacterial infections." (PMID 32316261, 2020). "Hyperthermia and elevation of plasma TNF-α levels occurred within 24 h of bacterial infection." (PMID 32221396, 2020). "Recently, it was reported that bacterial infections may activate silent nociceptors via cytokine production (including TNF-α and IL-1β), resulting in bladder hyperalgesia." (PMID 33574810, 2020). "In response to various stimuli, including proinflammatory cytokines tumor necrosis factor α (TNFα) and interleukin-1β (IL-1β), lipopolysaccharides (LPS), and the viral or bacterial infections, the IκB proteins are rapidly phosphorylated by upstream IκB kinases (IKKs)." (PMID 33469458, 2020). "Piliponsky37 also showed TNF-α from basophils could enhance the innate immune response against bacterial infection." (PMID 31988281, 2020).
bacterial infection (continued). "Moreover, the upregulated levels of proinflammatory cytokines IL-1β, IL-6 and TNFα in the serum of mice infected by SL1344 manifested their stronger resistance to bacterial infection, which implied that the SL1344 had posed higher virulence to hosts." (PMID 30898022, 2019). "The production of a number of cytokines by matured monocytes, such as tumor necrosis factor-alpha (TNF-alpha) and IL-6, plays an important role in the initiation of the acquired immune response, creating an inflammatory environment favorable for fighting a bacterial infection." (PMID 31027390, 2019). "In the mouse model of bacterial infection, evodiamine efficiently increased the serum levels of IL-1β, TNF-α and IFN-γ, thus potentiating the innate immune responses to enhance the clearance of bacteria and dampening the infiltration of inflammatory cells in the liver." (PMID 30971927, 2019). "By utilizing an improved Tol2 transposon system, the transgenic fish has enhanced bacterial resistance against V. vulnificus and Streptococcus agalactiae and immunomodulatory effect was observed such as downregulation of IL-1β and TNF-α at 12 h post bacterial infection." (PMID 31824449, 2019). "Moreover, the CF embryos presented a delayed immune response following bacterial infection in comparison to the WT, as shown by significantly reduced TNF-α and IL-β activation at 8 hpi." (PMID 30728389, 2019). "TNF-α and IL-6 are typical pro-inflammatory cytokines and have been used as potential markers for ongoing bacterial infections in piglets, while IL-22 is essential for maintaining mucosal barrier homeostasis against specific pathogens by eliciting innate defense response." (PMID 31286936, 2019). "Since exhaustive exercise inhibits systemic tumor necrosis factor-α (TNF-α) production that normally occurs in a bacterial infection model (injection of lipopolysaccharide [LPS]), immunodepression after strenuous exercise is involved in increased susceptibility to microorganism infection." (PMID 31480668, 2019). "Although IFNγ production may be maintained in ESRD patients through IL-12/IL-18 stimulation of MAIT cells, the lower levels of TNFα production in response to microbial stimulation point to defects in the response to bacterial infection." (PMID 29868028, 2018). "Furthermore, macrophages produce a large variety of cytokines, including tumor necrosis factor-α, interferon-β, and interleukin-6 following pathogen engulfment, and these cytokines activate both innate and adaptive immune responses to bacterial infection." (PMID 29942306, 2018). "Furthermore, TNF-α is produced early in bacterial infection as a Trojan horse to ensure their intracellular replication." (PMID 29500439, 2018). "An anti-inflammatory function of the TNF/TNFRp55 pathway in DCs might contribute to the protection against ReA during the resolution of bacterial infection." (PMID 29494692, 2018). "The reduced expression of pro-inflammatory cytokines, such as IL-1β, IFN-γ and TNF-α, may also reflect the fact that bacterial infection was suppressed in BDL Tg mice." (PMID 30149550, 2018). "TNF is a major driver of bacterial infection suggesting that necroptosis may also appear to be a pro-inflammatory factor in bacterial infection-induced inflammation." (PMID 29980212, 2018). "Macrophages activated by inflammatory stimuli such as LPS in bacterial infections secrete pro-inflammatory cytokines such as TNF-α, IL-1, IL-6 and other soluble mediators such as nitric oxide (NO), which play a crucial role in induction and progression of the inflammatory response." (PMID 29141025, 2017). "To investigate whether Mincle suppresses bacterial infection, we examined the production of TNF-α and IL-6 by BM neutrophils infected with live E. coli." (PMID 28112221, 2017). "As UBE2L3 affected pro-IL-1β protein in response to LPS, PAM3CSK4, and TNF, we asked whether it altered pro-IL-1β produced in response to natural bacterial infection." (PMID 28147281, 2017).